PRL (prolactin)
Diseases named in the same sentence as PRL in open-access papers (continued):
Sharing a sentence is not in itself a finding about the gene and the disease.
vitamin D deficiency (7 papers, 2020 to 2026). A nutritional condition produced by a deficiency of VITAMIN D in the diet, insufficient production of vitamin D in the skin, inadequate absorption of vitamin D from the diet, or abnormal conversion of vitamin D to its bioactive metabolites. "Previous studies suggest that vitamin D deficiency attenuates the prolactin-lowering effect of metformin in women." (PMID 41978113, 2026). "Previous studies have found a negative correlation between 25(OH)D and Hcy levels in the general population and in women PRL, and both vitamin D deficiency and hyperhomocysteinemia are risk factors for atherosclerotic disease and adverse pregnancy outcomes." (PMID 41019558, 2025). "Females with vitamin D deficiency (group A), vitamin D-insufficient women (group B) and vitamin D-sufficient women (group C) were matched for age, body mass index, blood pressure and prolactin levels." (PMID 40507082, 2025). "Although observed in all study groups, the decrease in prolactin levels was less pronounced in women with concomitant vitamin D deficiency, and follow-up levels of this hormone differed between patients with low vitamin D status and women with normal vitamin D status." (PMID 37242186, 2023). "Secondly, between-group differences in lowering prolactin levels suggest that cabergoline-resistant hyperprolactinemic patients should be evaluated for vitamin D deficiency/insufficiency, and if subnormal concentrations are detected, exogenous calciferol should be supplemented." (PMID 37242186, 2023).
cardiac hypertrophy (6 papers, 2016 to 2025). "PRL injections in the short photoperiod-housed hamsters induced renal hypertrophy simulating long photoperiodic induction." (PMID 40635655, 2025). "It is tempting to speculate that downregulation of these gene products contributed to the reduction of prostate hypertrophy induced by WS® 1541 in the Pb–PRL model." (PMID 30984003, 2019). "PRL treatment induced cardiac dilatation and cardiac hypertrophy in CM-KO but not in CTRL mice." (PMID 34548576, 2021).
deficiencies (6 papers, 2018 to 2025). "Concerning prolactin and somatotropin deficiencies, they were detected in four (9.1%) and in two cases (4.5%), respectively." (PMID 37391784, 2023). "Mutations in POU1F1 are known to result in a phenotype of GH, TSH, and prolactin deficiencies (usually severe) with a small or normal anterior pituitary (AP) on magnetic resonance imaging (MRI)." (PMID 35262704, 2022). "Most of the previous works were done in mouse model with multiple pituitary deficiencies (GH, PRL, and thyrotropic hormones), making it difficult to identify the precise role of each hormone." (PMID 29928261, 2018). "Patients with previously reported POU-homeodomain-truncating variants clinically presented with autosomal recessive early-onset and severe TSH, GH, and PRL deficiencies, similar to the clinical course observed in our patients, which supports the pathogenic nature of the c.744-5_749del11bp variant." (PMID 35456463, 2022). "Growth hormone (GH), prolactin (PRL), TSH, LH, and FSH deficiencies were diagnosed by baseline hormone levels of the pituitary and its peripheral hormones." (PMID 33977343, 2021). "Therefore, we recommend including prolactin testing in the diagnostic workup for patients with GH and TSH deficiencies." (PMID 40141050, 2025). "A de novo heterozygous mutation (c.811C > T, p.R271W) was subsequently detected in the gene encoding POU1FI (PIT1), accounting for his severe GH, TSH, and prolactin deficiencies; however, this could not explain the putative ACTH and gonadotropin deficiencies." (PMID 35262704, 2022).
Dyskinesia (6 papers, 2018 to 2024). A movement disorder which consists of effects including diminished voluntary movements and the presence of involuntary movements. "Lisuride has been approved in Europe for more than 40 years for the treatment of parkinsonian symptoms and dyskinesias or to lower prolactin level." (PMID 38212441, 2024). "Moreover, female PwP with wearing-off phenomenon and dyskinesia were shown to have higher levels of prolactin." (PMID 37545736, 2023). "The best model built with assay activity data alone is for the ADE “blood prolactin increased” and the ADE “dyskinesia” at therapeutic dose (ADET) with AUC-ROC values of 0.72 and 0.69, respectively." (PMID 29491351, 2018).
Dysmenorrhea (6 papers, 2014 to 2026). Pain during menstruation that interferes with daily activities. "In the present study, the modulation of hsCRP, cortisol, and prolactin levels in patients with dysmenorrhea was significantly improved after the completion of a 10-week HIIT exercise, but not as a result of probiotic supplementation." (PMID 40004951, 2025). "Compared with those in normal volunteers, the PRL, LH, TEST, and E2 levels were higher in the dysmenorrhea patients before treatment (P < 0.01)." (PMID 24834101, 2014). "The results showed that the PRL, TEST, and E2 levels were higher in the dysmenorrhea group than in the healthy groups (P < 0.01)." (PMID 24834101, 2014). "The results showed that changes in PRL, LH, TEST, PROG, and E2 concentrations are correlated with dysmenorrhea." (PMID 24834101, 2014). "In our study, young female basketball players experiencing dysmenorrhea exhibited higher EAT-26 scores, suggesting greater susceptibility to DEAs, along with elevated serum concentrations of prolactin and cortisol, compared to their non-dysmenorrheic counterparts." (PMID 40218947, 2025).
Fibroadenoma (6 papers, 1987 to 2026). A benign tumor of the breast characterized by the presence of stromal and epithelial elements. "Differential diagnoses for GG with normal prolactin levels may include infectious mastitis, juvenile breast hypertrophy and/or normal pregnancy changes, benign breast conditions such as fibrocystic change or fibroadenoma, and underlying malignancy." (PMID 26713166, 2015). "Mutated PRLRs can be detected in fibroadenomas, and the mutation in the PRLR is associated with increased serum PRL levels." (PMID 36845388, 2023). "Additionally, this patient had a history of elevated prolactin levels and a benign right breast fibroadenoma (measuring ~2.5 cm, confirmed histologically), followed by left-sided milk congestion managed via incision and drainage." (PMID 41496136, 2026). "Moreover, elevated serum PRL levels could be observed in patients with fibroadenomas or phyllodes tumours." (PMID 36845388, 2023). "PRL did not stimulate colony formation in primary cultured fibroadenoma." (PMID 36845388, 2023).
gonadotroph adenoma (6 papers, 2015 to 2024). "Their downregulation was also found in PRL and gonadotroph adenomas, suggesting that it represents a general event in pituitary tumorigenesis." (PMID 26137461, 2015).
Hypocalcemia (6 papers, 2012 to 2025). An abnormally decreased calcium concentration in the blood. "These authors also demonstrated that circulating PRL causes prolactin receptor expression in the hypothalamus, suggesting a preventive role against stress-induced hypocalcemia and ulcerogenesis." (PMID 22291890, 2012). "Four out of five males presented with primary hypogonadism, four out of five with mildly elevated prolactin, three out of seven with hypocalcemia, and five out of seven with elevated levels of insulin growth factor 1 (IGF-1)." (PMID 32575417, 2020). "Fujikawa showed that PRL levels increase in response to stress acting on the central nervous system to protect against acute stress-induced hypocalcemia." (PMID 24225037, 2013).
insulinoma (6 papers, 2019 to 2024). "It should also be noted that prolactin is involved in the upregulation of pancreatic beta cell mass, stimulating pancreatic beta cell replication in pancreatic islets as well as insulinoma cells." (PMID 38339098, 2024). "Her history started with a hypophyseal tumor producing prolactin 10 years before her surgery for insulinoma, which was treated by irradiation." (PMID 37629713, 2023). "Children with MEN1 most frequently present with pituitary (prolactin-secreting) and pancreatic (gastrinomas, insulinomas, and non-functional) NENs, in addition to primary hyperparathyroidism which is not currently classified as an NEN." (PMID 36291833, 2022). "The process of tumour detection involved biochemical screening tests including gastrin, glucose, insulin, chromogranin-A, pancreatic polypeptide, glucagon, vasointestinal polypeptide, prolactin and IGF-1 to assess for gastrinoma, insulinoma, enteropancreatic and anterior pituitary tumours." (PMID 31797261, 2020).
liver disease (6 papers, 2015 to 2025). "PRL levels are notably elevated in patients suffering from hepatic encephalopathy, a serious complication associated with liver disease." (PMID 41476991, 2025). "Elevated PRL levels have been linked to increased mortality rates, highlighting its potential role as a prognostic marker in liver disease." (PMID 41476991, 2025). "Prolactin holds a promising perspective in treating metabolic and advanced liver diseases." (PMID 35860276, 2022). "Other medical diseases including CKD and liver disease must also be ruled out as prolactin is cleared by the kidney (25%) and liver (75%) with organ dysfunction resulting in buildup of the hormone." (PMID 27446618, 2016). "This elevation in PRL levels is not correlated with factors such as antiretroviral therapy (ART), metabolic disturbances, liver disease, or viral load." (PMID 41476991, 2025).
mental disorder (6 papers, 2018 to 2024). A disease that has its basis in the disruption of mental process. "It is suggested that the combination of D-dimer, homocysteine and prolactin has high diagnostic value for VTE in patients with mental disorders." (PMID 38827445, 2024). "In patients with manic episodes, the long LOS group was younger, had an earlier start and a longer duration of the disease, had a larger percentage of unmarried status, psychotic features, and a family history of mental disorders, and had a lower PRL level than the short LOS group (all p < 0.1)." (PMID 36936616, 2023). "In addition, since UNC9994 has exerted antipsychotic-like activity in mice, it may represent an interesting, new and unique pharmacological therapy in patients, with PRL-PitNETs, as antipsychotic drugs for mental disorders." (PMID 37370829, 2023). "In our results, therapeutic targets or biomarkers of neurological disorder and mental disorder, such as DRD1, DRD2, DRD4, HTR2A, PRL and ADRA2A, were assigned with high scores in both mirtazapine and pramipexole." (PMID 29371651, 2018).
mood disorder (6 papers, 2017 to 2025). A cognitive disorder a disturbance in which the person's mood is hypothesized to be the main underlying feature. "Research focusing on neurotransmitter changes could provide insights into the link between prolactin dysregulation and mood disorders." (PMID 41510476, 2025).
pituitary disease (6 papers, 2022 to 2024). "Out of the 1253 patients who underwent serial PRL sampling, 139 patients (101 women and 38 men) met the inclusion criteria: 106 (76.3%) patients had some form of pituitary disease, with microlesions observed in 69.8%, macrolesions in 25.5% and other findings in 4.7% of subjects." (PMID 38194218, 2024). "After excluding individuals with known pituitary diseases, PRL ≥ 35 ng/ml, and PRL-altering drugs including antipsychotic agents, selective serotonin reuptake inhibitors, or dopamine agonists, 5,086 data points (2,845 in phase-1 and 2,241 in phase-2) were available for analysis." (PMID 38829475, 2024).
renal failure (6 papers, 2017 to 2024). "One patient had previously suffered from severe renal insufficiency, and during that time, prolactin increased." (PMID 34441908, 2021).
asthma (5 papers, 2018 to 2025). "In this sense, this review aims to explore the potential involvement of PRL in asthma pathophysiology by examining its interactions with intracellular signaling pathways and its possible impact on airway smooth muscle contractility and immune modulation." (PMID 40806464, 2025). "It was established that the therapeutic effect observed was induced by six metabolites and the prime targeted candidate to suppress asthma-related genes was related to the prolactin signaling pathway." (PMID 40806464, 2025). "Although a significant difference has not been observed, this does indicate a possible relation between prolactin and asthma symptomology that warrants further study." (PMID 40806464, 2025). "These facts suggest the participation of prolactin in the pathogenesis of asthma by impacting the immune function and promoting airway smooth muscle contraction through intracellular signaling pathways." (PMID 40806464, 2025). "Despite evidence that PRL can have effects in the lungs and airways, its specific role in asthma pathophysiology remains poorly understood and largely unexplored in clinical settings." (PMID 40806464, 2025). "Although little is known, emerging evidence suggests that PRL could be involved in asthma by modulating immune cell function and promoting a proinflammatory state." (PMID 40806464, 2025). "Because prolactin levels are also altered during menopause, they may also contribute to asthma pathophysiology." (PMID 40806464, 2025). "In this sense, although little is known of the role that prolactin (PRL) could potentially play in asthma, there are clear indications that, since the airway is subjected to hormonal control, PRL could also participate in the pathophysiology and merits further research." (PMID 40806464, 2025). "Therefore, in the present paper, we cover the potential role that PRL may play in asthma by promoting inflammation and modulating immune responses." (PMID 40806464, 2025). "However, in asthma, PRL might be involved in promoting inflammation and modulating immune cell activity." (PMID 40806464, 2025). "At the end of the study, the treated group reported a significant improvement in asthma and rhinitis symptoms and lower serum levels of eosinophil cationic protein (ECP), IL-13, PRL, and adrenocorticotropic hormone (ACTH)." (PMID 40806464, 2025). "ESR1 participates in two primary KEGG asthma pathways: the B-Cell signaling pathway and the JAK-STAT signaling pathway, through the Prolactin signaling pathway (KEGG)." (PMID 32185106, 2020). "In contrast, another study, involving 86 children with mild asthma treated either with sublingual immunotherapy (SLIT) or given a placebo for 6 months, showed that lower symptoms might be related to the reduction in PRL and the consequent lower activation of T lymphocytes." (PMID 40806464, 2025). "The Prolactin signaling pathway, targeted by ESR1, activates pathways involved in the inflammatory response including the KEGG secondary MAPK pathway and PI3K pathway and is also involved in the secondary KEGG asthma NF-κB signaling pathway; with ESR1 again acting downstream (KEGG)." (PMID 32185106, 2020).
autism (5 papers, 2011 to 2025). Persistent deficits in social interaction and communication and interaction as well as a markedly restricted repertoire of activity and interest as well as repetitive patterns of behavior. "In another study of adolescent patients with autism, prolactin levels were found to be lower in the low-dose risperidone group than in the high-dose risperidone group." (PMID 37403159, 2023). "To understand changes in PV and PNN levels in the VPA model of autism, we first examined the densities of PV+ neurons and PNN in PrL-PFC in saline and VPA mice." (PMID 33912009, 2021).
autoimmune hypothyroidism (5 papers, 2020 to 2025). "In line with this explanation, titers of TPOAb and TgAb, which determine the severity of Hashimoto thyroiditis, inversely correlated with the impact of metformin on total and monomeric prolactin." (PMID 39204081, 2024). "Recently, our research team reported that coexisting autoimmune (Hashimoto) thyroiditis mitigated the impact of metformin on the secretory function of the anterior pituitary cells of women, including attenuation of the prolactin-lowering effect." (PMID 39204081, 2024). "The most likely explanation for a mitigatory impact of Hashimoto thyroiditis on the prolactin-lowering effect of metformin is interaction at the level of the pituitary adenosine 5′-monophosphate-activated protein kinase (AMPK) pathway." (PMID 39204081, 2024). "In another study, PRL was found to be significantly elevated in the patients with Hashimoto's thyroiditis which is introduced by autoantibodies targeting thyroid." (PMID 32597541, 2020). "In women diagnosed with Hashimoto’s disease, cabergoline’s effects were limited to a reduction in prolactin levels, HOMA1-IR, and UACR, as well as an elevation in HDL cholesterol, with these alterations being less pronounced compared to women without thyroid illness." (PMID 39852352, 2025). "However, the role of prolactin excess cannot be completely ruled out in subjects with autoimmune hypothyroidism, not included in our study because of the association between thyroid hypofunction and increased prolactin production." (PMID 37375719, 2023). "Undoubtedly, a novel observation of our present study is that the impact on prolactin concentration was absent in men with concurrent euthyroid Hashimoto thyroiditis." (PMID 39204081, 2024). "More importantly, this study has shown for the first time that prolactin-lowering properties of metformin were absent in individuals with coexisting Hashimoto’s thyroiditis." (PMID 37297964, 2023).
Breast enlargement (5 papers, 2015 to 2024). "In Group 2b (pregnancy related), possible mechanism of gigantomastia is increased sensitivity to prolactin in mammary gland." (PMID 27195157, 2016). "Since most cases of gigantomastia occur during puberty or pregnancy, one possible etiology is the excessive release of estrogen or prolactin." (PMID 26713166, 2015). "In the first case, gigantomastia has started in pregnancy and PRL level was minimally increased." (PMID 27195157, 2016). "The authors suggested that estrogen receptor sensitivity to prolactin might have accounted for breast hypertrophy and enlargement." (PMID 26713166, 2015). "Considering the range of differential diagnoses for a woman presenting with gigantomastia in pregnancy, a thorough workup should include white blood cell count, hematocrit level, platelet count, electrolyte panel, hormone profile (estrogen, progesterone, and prolactin), and tissue biopsy." (PMID 26713166, 2015). "In our study, prolactin levels were higher in infants with breast enlargement than in those without breast enlargement and they were highly significantly correlated (p=0.006)." (PMID 26831552, 2015).
chronic heart failure (5 papers, 2015 to 2025). "However, whether prolactin elevation is a causal factor of chronic heart failure remains to be elucidated." (PMID 35923071, 2023). "The scope of this work was to examine the role of Mediterranean diet on erectile function and cardiovascular hemodynamics, in patients with chronic heart failure, in order to illustrate central and peripheral vessel rheology and prolactin physiology." (PMID 33396861, 2020).
cognitive decline (5 papers, 2014 to 2025). "Moreover, PRL exerts both pro- and anti-inflammatory effects within the central nervous system, and neuroinflammation is increasingly recognized as a contributor to cognitive decline." (PMID 41470032, 2025). "Additionally, in rats PrL is innervated by noradrenergic axons, and degeneration of such projections to homologous regions in PD may contribute to cognitive decline." (PMID 39474461, 2024).
colon carcinoma (5 papers, 2007 to 2025). "Similarly, PRL-induced signaling was only observed in colon cancer cells and cell lines with a higher PRL receptor expression than in normal colonic epithelial cells." (PMID 33557010, 2021).